NGF (nerve growth factor)
Diseases named in the same sentence as NGF in open-access papers (continued):
Sharing a sentence is not in itself a finding about the gene and the disease.
Cognitive impairment (continued). "The dysfunction of cholinergic neurons is related to cognitive defects, and mature cholinergic neurons in the basal forebrain are highly dependent on NGF signals." (PMID 34720898, 2021). "By contrast, MMSE and MoCA scores in PD patients were positively correlated with NGF and BDNF levels and negatively correlated with NSE levels, confirming these close associations with PD severity and cognitive impairment." (PMID 33329296, 2020). "Thereby, cognitive impairments after muscle regeneration were associated with an increase of brain BDNF level and a decrease of brain NGF level." (PMID 32066806, 2020). "Gradual age-related loss of cholinergic function results from decreased trophic support from nerve growth factor (NGF) and degeneration of dendritic, axonal and synaptic structures, which cause brain function decline, including cognitive impairment." (PMID 29681847, 2018). "The idea is that cognitive deficits in AD are related to change of BDNF blood level as well as that of other neurotrophic factors such as the nerve growth factor and GDNF in blood." (PMID 28289378, 2017). "A shift inthe proNGF/NGF ratio towards precursor prevalence is regarded as the mainreason for cholinergic deficit, leading to cognitive impairment." (PMID 28740732, 2017). "In particular, alterations of the NGF signalling system in the basal forebrain correlate more robustly than the amyloid load with cognitive deficits in mild cognitive impairment (MCI) and with MCI progression towards AD." (PMID 27076121, 2016). "Improved attention and working memory in animal models and patients with mild cognitive impairment, increased the levels of NGF and BDNF in rats." (PMID 26941642, 2016). "Moreover, exogenous NGF mitigates propofol-induced cognitive impairments and M1 polarization, reducing apoptosis and oxidative stress levels." (PMID 39869375, 2025). "Moreover, NGF can induce the onset of mental and cognitive disorders by regulating the dopamine D2-receptor activity, as well as by impairing oligodendrocyte formation/maturation and myelination." (PMID 38646100, 2024). "NGF is also known for its beneficial effect on recovery from cognitive deficits after brain damage." (PMID 38928583, 2024). "EA could suppress Rab5a‐GTP to promote the transduction of NGF signaling, and enhance the synaptic plasticity of the basal forebrain hippocampal circuit improving cognitive impairment in the early stage of 5 × FAD mice." (PMID 38780008, 2024). "A previous study also revealed that increased NGF and TrkA expression and activation of the Akt/GSK3β pathway could ameliorate brain hypoperfusion-induced cognitive impairment in rats." (PMID 35565989, 2022). "A recent study described that Aβ-induced MMP-3 may contribute to NGF degradation leading to cholinergic atrophy and cognitive deficits in AD males." (PMID 33986628, 2021). "We hypothesize that the decrease in brain NGF levels observed in FI mice 28 days after surgery, more than a marker of memory dysfunction, plays an active role in the processes leading to cognitive impairment after surgical intervention." (PMID 32066806, 2020). "Similarly, chungkookjang stimulated nerve growth factor secretion and nerve growth factor receptor signaling pathway in Tg2576 mice and in trimethyltin-induced cognitive defective mice." (PMID 31344808, 2019). "A missense mutation (R100W) in the beta-NGF gene was found in hereditary sensory autonomic neuropathy V (HSAN V) patients with severe loss of pain perception but without overt cognitive impairment." (PMID 30524266, 2018). "Induction of cell death was attributed to pro-NGF in primary superior cervical ganglion cultures, smooth muscle cells, and PC12 cells, and elevated levels of pro-NGF or pro-BDNF are observed in neurological disease states such as Alzheimer’s, autism, or cognitive impairment associated with HIV." (PMID 28273811, 2017). "The p75NTR-dependent apoptosis and cognitive defect could be fully reversed by NGF supplementation." (PMID 33966253, 2021).
Cognitive impairment (continued). "While NGF can regulate the growth of peripheral and central neurons, maintain neuronal survival and synapse structure stability, which binds to its high-affinity receptor TrkA to ameliorate progressive cognitive deficits, exerting the neuroprotective effect in AD." (PMID 30405422, 2018). "Another study conducted in APP/PS1 mice found that activation of the NGF-TrkA pathway induces neurogenesis, regulates the c-Raf/ERK1-2/CREB cascade response, reduces Abeta levels, and improves cognitive impairment." (PMID 39022312, 2024). "Research has also shown that co-transfection of nerve growth factor and TERT in bone marrow mesenchymal stem cells promotes recovery of cognitive impairment in vascular dementia rats." (PMID 39022312, 2024). "Abnormalities in NGF signaling caused by disruption of the structure of its receptors [TrkA (NTRK1 gene) and p75 (NGFR gene)] or the signaling pathways involved, may also impair brain morphogenesis and lay the groundwork for the onset of mental and cognitive disorders." (PMID 38646100, 2024). "Results of our study suggest that HupA can increase the hippocampal NGF, BDNF and NT-3 levels, which is related to its protective effect on cognitive impairment of rats after isoflurane anesthesia." (PMID 32049185, 2020). "Altogether, 26 patients (18 males and 8 females), revealed obvious cognitive impairment (MMSE scores ranged between 21 and 26), and they received NGF combined with pulsed steroids." (PMID 32391255, 2020). "EGCG increases NGF and CREB expression levels in APP/PS1 providing neuroprotection through ameliorating cognitive impairment in mice model, neuroprotection is also mediated by ERK1/2/ C-Raf by phosphorylating TrkA." (PMID 29896105, 2018). "The present research showed that lithium prevented cognitive impairment through reestablishment of BDNF, NGF, and GDNF expression." (PMID 29200666, 2017). "Any changes or alterations of neurotrophic factor level such as BDNF, NGF, and GDNF are related to cognitive deficit or impairment." (PMID 29200666, 2017). "As with NGF, BDNF therapy in animals by infusion or viral transfer seems to successfully ameliorate cognitive impairment." (PMID 22654716, 2011). "The emphasis is shifting toward early intervention, possibly even at the prodromal or mild cognitive impairment (MCI) stage, where NGF support could stabilize synaptic function and delay degeneration." (PMID 40656325, 2025). "Indeed, transgenic mice expressing an anti-NGF-antibody electively targeting mature NGF and leaving the proform unperturbed, exhibited accelerated BFCN pathology and cognitive impairments." (PMID 36397124, 2022). "However, recent studies uncovered that elevating the neurotrophin levels (such as BDNF, NGF and GDNF) in AD mice supports neuronal integration of grafted cells into the circuits, which improves the cognitive deficits." (PMID 36397124, 2022). "Specifically, both NGF maturation and degradation are disrupted at preclinical AD stages as revealed in individuals with no cognitive impairment (NCI) but with high brain β-amyloid (Aβ) levels (HA-NCI)." (PMID 34434101, 2021). "Such NGF dysmetabolism is well-established in Alzheimer’s brains with advanced pathology and has been observed in mild cognitive impairment (MCI) and non-demented individuals with elevated brain amyloid levels." (PMID 34434101, 2021). "The late cognitive impairments involving memorization process lead us to evaluate brain levels of two major central neurotrophic factors: brain derived neurotrophic factor (BDNF) and nerve growth factor (NGF)." (PMID 32066806, 2020). "A point mutation in the NGFB gene (leading to the amino acid substitution R100W) is responsible for Hereditary Sensory and Autonomic Neuropathy type V (HSAN V), leading to a congenital pain insensitivity with no clear cognitive impairments, but with alterations in the NGF/proNGF balance." (PMID 36979056, 2023).
Cognitive impairment (continued). "Moreover, the loss of NGF‐TrkA signaling “in the CNS”, obtained by conditionally deleting NGF or TrkA genes in CNS cells derived from nestin‐positive cells, has proven not to be sufficient in inducing severe cognitive impairments nor neurodegeneration in mice." (PMID 29473218, 2018). "Finally, the study did not include another relevant growth factor, Nerve Growth Factor (NGF) that might be accounting for the cognitive impairment described in AUD patients, and that should be analyzed in future studies." (PMID 34341419, 2021). "The changes in choline acetyltransferase activity and acetylcholinesterase however, are not seen in mild cognitive impairment (MCI) and it may be that they are a result of other changes in cholinergic cells, such as loss of TrkA and reduction of NGF, which have been reported in MCI." (PMID 22654716, 2011). "Bilateral intrahippocampal infusion of GQ1b, when administered after disease progression, restores cognitive impairments in 3xTg-AD mice accompanied by an increase in BDNF, but not NGF or NT-3 levels." (PMID 31186474, 2019).
diabetic neuropathy (61 papers, 2003 to 2025). A chronic, pathological complication associated with diabetes mellitus, where nerve damages are incurred due to diabetic microvascular injury involving small blood vessels that supply these nerves, resulting in peripheral and/or autonomic nerve dysfunction. "Epidermal keratinocytes are the primary source of NGF in the skin; lower dermal levels of NGF in patients with diabetic polyneuropathy are associated with neuropathic signs of sensor and autonomic nerve function." (PMID 41139799, 2025). "An increase in oxidative stress, activated inflammatory pathways, and a reduction in NGF are some of the general causes of diabetic neuropathy." (PMID 38916919, 2025). "NGF is thought to be the most significant neurotrophic factor for diabetic neuropathy and linked to morphological variation, neuron regeneration, and the expression of neurotransmitters." (PMID 36556476, 2022). "Diabetic neuropathy is associated with decreased NGF expression in human diabetic nerves and vitamin D3 is also known to induce NGF synthesis in human cell lines." (PMID 31031586, 2019). "Recent studies showed that neuritin expression increased following ischemia and reperfusion in rats and that it mediates NGF-induced axonal regeneration and is deficient in experimental diabetic neuropathy." (PMID 20634963, 2010). "In patients with diabetic neuropathy, many exhibit NGF deficiency." (PMID 38540203, 2024). "Beneficial effects of DG in a diabetic neuropathy model in restoring ultrastructural changes and neural regeneration might be associated with increased expression of NGF." (PMID 32215172, 2020). "While a decreased production of NGF in various tissues has been implicated in the pathogenesis of experimental diabetic polyneuropathy, in animal studies, impaired retrograde axonal transport of NGF is also partly responsible for the reduced nerve regenerative capacity." (PMID 30648113, 2018). "The most reasonable explanation for this clinical study failure and the interruption of NGF investigations in diabetic neuropathies could be associated with the necessity to use low NGF dosage (for side effects) in comparison with those of animal studies." (PMID 27439311, 2016). "Presently, anti-NGF therapy is predominantly utilized for chronic pain management in rheumatology and diabetic neuropathy settings." (PMID 38542008, 2024). "For instance, the application of nerve growth factor (NGF) has shown promising results in promoting nerve regeneration and functional recovery in diabetic neuropathy models." (PMID 39204115, 2024). "FMNT reduced diabetic neuropathy via reducing oxidative stress and increasing expression of sirtuin one and nerve growth factor (NGF)." (PMID 35662691, 2022). "In diabetic neuropathy, the function of NGF is impaired and the expression of NGF-related genes is modified, which are important factors in the progress of diabetic neuropathic pain." (PMID 35745079, 2022). "Although NT administration has been tested as a potential therapy in peripheral neuropathies (e.g., NGF to treat diabetic neuropathy), those trials were complicated by dose-limiting pleiotropic effects, such as pain." (PMID 34337561, 2021). "Previous studies have shown that NGF can reverse axonal degeneration, demyelination, and atrophy in diabetic neuropathy, and the efficacy of recombinant human NGF (rhNGF) has been tested in a phase III trial of patients with diabetic neuropathy." (PMID 32123299, 2020). "Patients with diabetic neuropathy showed not only decreased NGF level but also increased level of NGF." (PMID 28827818, 2017). "Other growth factors, such as insulin-like growth factor (IGF), nerve growth factor (NGF), and ciliary neurotrophic factor, were also investigated in experimental animals with diabetic neuropathy." (PMID 29098161, 2017). "NGF plays an important part in the pathomechanism of diabetic polyneuropathy and NGF has therapeutic feasibility for cardiomyopathy in diabetic subjects." (PMID 29285284, 2017).
diabetic neuropathy (continued). "The correlation between a reduced NGF level and the occurrence of diabetic neuropathy has been well documented." (PMID 28827818, 2017). "In diabetic neuropathy clinical trial, the systemically delivered doses of NGF had to be reduced below the pharmacologically effective dose, because of the strong pain induced in patients." (PMID 26371475, 2015). "In diabetic neuropathy, NGF levels are decreased in peripheral nerve such as superior cervical ganglion and sciatic nerve in STZ-induced rats." (PMID 25878713, 2015). "Previous studies have used neurotrophin, such as a NGF injection method, for overcoming diabetic neuropathy." (PMID 25878713, 2015). "It has also been shown that diosgenin can induce NGF expression in a mouse model of diabetic neuropathy." (PMID 26075266, 2015). "In our present and previous works, we investigated, for the first time, the relevance of NGF in the early establishment of diabetic neuropathy." (PMID 23710226, 2013). "NGF supply in animal models of diabetic neuropathies reverses neuropathic signs by normalizing the PNS activity." (PMID 23710226, 2013). "We also found that downregulation of cardiac NGF leads to diabetic neuropathy, and that NGF supplementation rescues silent myocardial ischemia in DM." (PMID 21037846, 2009). "Additionally, research has revealed that the severity of sensory impairment is connected with the levels of NGF in the skin of individuals with diabetic neuropathy, which have been shown to be significantly lower." (PMID 36556476, 2022). "In diabetic polyneuropathy recombinant human (rh) NGF, BDNF and NT3 have had limited benefits." (PMID 36362354, 2022). "NGF signaling pathway which is related to diabetic neuropathy was amongst the enriched pathways." (PMID 34873190, 2021). "From the results, it can be concluded that Triphala churna has beneficial effects in diabetic neuropathy which may be attributed to decreased oxidative stress, inhibition of inflammatory cytokines and increased expression of NGF in rats." (PMID 34149415, 2021). "Furthermore, the administration of exogenous nerve growth factor leads to an improvement in diabetic neuropathy." (PMID 33669048, 2021). "Neutralizing antibodies against VEGF and NGF negated the effects of hDPSC transplantation on the nerve conduction velocity in diabetic mice, suggesting that VEGF and NGF may play roles in the effects of hDPSC transplantation on diabetic polyneuropathy." (PMID 32546222, 2020). "Furthermore, the rates of many growth factors such as NGF are clinically very high in chronic pain conditions (arthritis, diabetic neuropathy, chronic headaches, and cancer pain)." (PMID 33015629, 2020). "Nerve growth factor (NGF), which is essential for primary nociceptive neuron development, was found by immunostaining to correlate with skin axon reflex vasodilation mediated by small sensory fibers in diabetic neuropathy patients." (PMID 30116739, 2018). "However, these authors found that NGF levels decrease proportionally to the severity of diabetic neuropathy." (PMID 28841856, 2017). "Alterations in NGF may also contribute to the development of diabetic neuropathy, as shown in animal models where NGF levels are reduced." (PMID 28841856, 2017). "Notably, patients with diabetic neuropathy have lower serum NGF levels than controls, and the decrease in NGF is reported to be proportional to decreases in a patients’ nerve conduction velocity." (PMID 28122008, 2017). "NGF also reversed peripheral neuropathic signs in animal models of diabetic neuropathy." (PMID 27438594, 2016). "Indeed, the large phase 3 diabetic neuropathy NGF clinical trial failed because the threshold of the administered hNGF WT, that provoked pain in patients, coincided with the minimal pharmacologically effective dose (1 μg/kg)." (PMID 26371475, 2015). "Our working hypothesis, therefore, is that the possible action of EA on diabetic neuropathy could be mediated through the NGF signaling pathway." (PMID 23710226, 2013).